USP39 (ubiquitin specific peptidase 39)
Diseases named in the same sentence as USP39 in open-access papers (continued):
Sharing a sentence is not in itself a finding about the gene and the disease.
tumor (continued). "Lactate promotes CTLA-4 expression in a Foxp3-dependent manner and promotes ubiquitin-specific peptidase 39 (USP39)-mediated RNA splicing in tumor-infiltrating Treg cells." (PMID 39464313, 2024). "Our study elucidates and describes how USP39 regulates pyruvate metabolism through a deubiquitylation process that affects NSCLC tumor growth." (PMID 39695108, 2024). "Immunoblotting of tissues clearly indicated the high expression of RBM39 and USP39 in tumor tissues and their protein levels also had a positive correlation with a Pearson’s correlation coefficient of 0.45." (PMID 39260689, 2024). "The results indicated that the expression level of USP39 in EC tumor tissue was dramatically higher than that in the normal endometrium." (PMID 38459014, 2024). "The expression of USP39 in non-tumor samples (n = 23) was much lower than that in EC tumor samples (n = 552) (P < 0.05), and higher expression of USP39 was positively correlated with the clinical grade and FIGO stage of EC (P < 0.05)." (PMID 38459014, 2024). "Compared to DEGs regulated by USP39 in tumors, more DEGs regulated by USP39 in non-tumors overlapped and had positive correlation with tumorigenesis-related DEGs, suggesting that USP39 mainly played a tumorigenic role during the early stage of tumor formation." (PMID 37821439, 2023). "Elevated USP39 expression in tumor tissues at both the protein and mRNA levels has also been demonstrated in previous studies." (PMID 37821439, 2023). "DAS events affected by USP39 participate in a wide range of tumor-related functions such as cell cycle control." (PMID 37821439, 2023). "We the evaluated the correlation between SIRT7 and USP39 and a positive correlation between the expression of SIRT7 and USP39 was verified in the tumor tissues of CSCC patients." (PMID 37957720, 2023). "In the future, the therapeutic influence of specific inhibitors on CSCC tumor tissue genesis will be explored by analyzing the effect of USP39-specific acetylation on SIRT7/USP39/FOXM1 positive feedback axis." (PMID 37957720, 2023). "In the U87‐ov‐USP39‐bearing tumor, the expression levels of USP39 and ADAM9 were upregulated but the expression levels of integrin β1 were downregulated compared with those in the U87‐ov‐Con‐bearing tumor." (PMID 33811456, 2022). "The result in tumor differentiation analysis indicated that only the expression level of USP39 was tightly correlated with tumor differentiation in which the high USP39 expression is related to poor tumor differentiation in general." (PMID 36582601, 2022). "The survival curve showed that overexpression of USP39 in U87 cells reduced the survival of the tumor‐bearing mice (P < 0.05)." (PMID 33811456, 2022). "Histological examination revealed that the tumor area in U87‐ov‐USP39‐bearing brain was larger than that in U87‐ov‐Con‐bearing brain at 25 days after cell injection; U87‐ov‐USP39 orthotopic xenografts tended to be more invasive than U87‐ov‐Con." (PMID 33811456, 2022). "Our study showed that USP10, USP14, USP18, USP32, USP33, and USP39 (termed as six-USPs) expressions were significantly elevated in tumor tissues." (PMID 36582601, 2022). "Conversely, USP39 knockdown inhibited proliferation in tumor size and weight of SK-hep-1 cells transfected with shTRIM26." (PMID 33649471, 2021). "The downregulation of USP39 expression in HCC cells significantly inhibited tumor growth, by reducing the volume and weight of tumors." (PMID 33649471, 2021). "The expression of USP39 showed significant correlation with T stage, pathologic stage, tumor status, age, and histologic grade." (PMID 34987596, 2021). "Herein, we found that overexpression of USP39 was significantly correlated with neoplasm stage, histological grade, and tumor size." (PMID 33718205, 2021). "The analyses of two independent cohorts showed consistently that USP39 expression was elevated in tumor tissues compared with their paired adjacent normal tissues." (PMID 34123832, 2021).
tumor (continued). "For the clinical investigation, USP39 overexpression was correlated with neoplasm stage, histological grade, and tumor size of HCC patients in LIHC cohort." (PMID 33718205, 2021). "As expected, immunohistochemical (IHC) staining revealed a significant increase of USP39 expression, and a high level of USP39 was correlated with advanced tumor stage and platinum resistance in HGSOC." (PMID 33731694, 2021). "The results showed that overexpression of USP39 in HEY cells led to an increased number of tumor nodes in the abdominal cavity." (PMID 33731694, 2021). "Consistent with previous reports, these results further consolidated USP39 as a promoter in tumor progression including HCC." (PMID 33649471, 2021). "USP39 acted as a pro-tumor factor by motivating the malignant biological processes of RCC, probably through inhibiting VEGF-A165b alternative splicing and regulating SRSF1 and SRPK1." (PMID 34544400, 2021). "Consistent with this, mice injected with ID8 cells with USP39 knockdown had a significant reduction in tumor burden." (PMID 33731694, 2021). "In recent years, it has been reported that USP39 was involved in tumor proliferation and metastasis through a variety of other mechanisms." (PMID 34987596, 2021). "T stage (P = 0.006), pathologic stage (P = 0.009), tumor status (P = 0.006), age (P = 0.043), and histologic grade (P = 0.002) were significantly correlated with high USP39 mRNA expression level." (PMID 34987596, 2021). "As expected, forced expression of USP39 in HEY cells induced a significant increase in tumor mass and volume." (PMID 33731694, 2021). "Together, these data indicate that USP39 functions as a tumor promotor and positively regulates lung tumor growth." (PMID 33255748, 2020). "Xenograft tumors of the USP39 KD group exhibited smaller tumor volumes compared with tumors of control and control sh groups." (PMID 33255748, 2020). "Bioluminescence signals did increase overall in mice over the 20-day time period, but USP39 knockdown led to a decreased rate in tumor growth." (PMID 31332287, 2019). "In addition, similar to other members of the USP family, USP39 can also directly or indirectly bind to tumor regulatory molecules to prevent degradation of specific proteins by removing the attached ubiquitin chains from their amino acid residues." (PMID 40672756, 2025). "miR-381 negatively regulates USP39 expression to control tumor proliferation and invasion." (PMID 40990019, 2025). "Additionally, USP39 can indirectly influence tumor progression by regulating abnormal glycolysis, glutamine metabolism, and tumor angiogenesis." (PMID 40672756, 2025). "Western blot analysis showed that when USP39 was knocked down, caspase 3 and PARP were activated, leading to apoptosis in tumor cells, demonstrating that USP39 can indirectly affect tumor development by regulating the expression levels of key apoptotic proteins." (PMID 40672756, 2025). "Furthermore, G‐749 is screened and identified as a novel NAT10 inhibitor capable of effectively impeding lysosomal acidification and tumor metastasis by disrupting the NAT10‐Ubiquitin‐specific Peptidase 39 (USP39) interaction." (PMID 40729677, 2025). "Constant suppression of USP39 resulted in major impairment of tumor growth and tumor weights." (PMID 39695108, 2024). "We then examined whether the EC tumor suppression effect of the treatment with the histone lactylation inhibitor 2-DG could be reversed by increased USP39 levels." (PMID 38459014, 2024). "We further present that USP39 silencing caused an elevation in Lys63 ubiquitination on PDHA and a reduction in the PDH complex activity, the levels of TCA cycle intermediates, mitochondrial respiration, cell proliferation in vitro, and of tumor growth in vivo." (PMID 39695108, 2024). "For instance, the enzyme USP39 promotes mTORC2 activation, further enhancing tumor progression." (PMID 39742278, 2024). "Mechanically, histone lactylation stimulated USP39 expression to promote tumor progression." (PMID 38459014, 2024).
tumor (continued). "In addition, we observed that the migration ability of EC tumor cells was enhanced after USP39 overexpression, as measured by Transwell assays." (PMID 38459014, 2024). "USP39 and possibly other mid/late-acting spliceosome components may serve as tumor biomarkers and therapeutic targets." (PMID 37821439, 2023). "Similarly, IHC assay also identified the higher USP39 expression in the tumor tissues of CSCC patients." (PMID 37957720, 2023). "USP39 is originally found as a regulator of RNA splicing in the tumor progression." (PMID 36707504, 2023). "The deletion of PSMD14 and USP39 significantly inhibited tumor growth." (PMID 35627203, 2022). "Experimental data showed that USP39 was a direct target of miR-381, and miR-381 could negatively regulate the expression of USP39 to control tumor proliferation and invasion." (PMID 36046375, 2022). "Accordantly, a previous study suggested the tumor-promotive role of USP39 in HCC cell lines." (PMID 33718205, 2021). "USP39 promotes proliferation/invasion in vitro and tumor growth in vivo." (PMID 33731694, 2021). "Thus, our results propose that Rictor constitutes a key target of USP39 in ESCC where it plays an essential role in regulating mTORC2-mediated signaling to promote tumor cell proliferation." (PMID 34123832, 2021). "It is reported in the literature that USP39 acts as a type of pro-tumor gene." (PMID 34544400, 2021). "Indeed, immunohistochemical analyses showed the upregulation of USP39 in ESCC was positively correlated with tumor differentiation status, invasion, lymph node metastasis and TNM stage." (PMID 34123832, 2021). "Furthermore, in vivo studies have confirmed that USP39 effectively modulates tumor growth." (PMID 40672756, 2025). "Furthermore, USP39 knockdown resulted in the inhibition of tumor growth in xenografts in nude mice, accompanied by a reduction in the expression levels of forkhead box protein M1 (FoxM1) and its target genes polo-like kinase 1, cyclin B1, and centromere protein A." (PMID 40990019, 2025). "Furthermore, it was discovered that USP39 functions not only as a splicing factor and regulator of mRNA maturation but also as a novel deubiquitinating enzyme of Cyclin B1, thereby participating in the proliferation of tumor cells." (PMID 40990019, 2025). "Therefore, USP39 could reasonably be regarded as a promising biomarker for the early detection and surveillance of tumor progression." (PMID 40672756, 2025). "Altogether, these results prove that USP39 may exert a tumor-promoting property in ESCC." (PMID 35627203, 2022). "Furthermore, TRIM26 silencing could significantly reverse the reduction of USP39 knockdown cell proliferation, in tumor size and weight." (PMID 33649471, 2021). "In addition, our microarray and bioinformatic analysis demonstrated that USP39 regulated diverse cellular signaling pathways that were involved in tumor biology, and several pivotal genes (IRF1, Caspase 8, and SP1) have been validated by quantitative real-time polymerase chain reaction." (PMID 30898977, 2019). "Conversely, USP39 interacted with and deacetylated USP39 via SIRT7, a SIRT-family NAD+-dependent deacetylase, thereby increasing USP39 stability and promoting HCC cell proliferation and tumor formation in vitro and vivo." (PMID 40990019, 2025). "Specifically, USP39 promotes HCC progression by inhibiting the degradation of ZEB1 through its deubiquitylation function, whereas TRIM26 exerts tumor suppressor functions by ubiquitinating degraded ZEB1." (PMID 40990019, 2025). "USP39 stabilizes SP1 protein and prolongs its half-life by promoting its deubiquitylation pathway to regulate cell cycle and tumor growth in HCC cells." (PMID 40990019, 2025). "Next, to investigate the effects of USP39 suppression on tumor growth, NCI-H1975 cells expressing USP39-targeting shRNA constructs were injected into immunodeficient mice." (PMID 39695108, 2024).
tumor (continued). "Both the expression of USP39 and the inclusion of KANK2 exon 2 were significantly increased in tumor samples compared to non-tumor samples in this in-house HCC cohort." (PMID 37821439, 2023). "Ubiquitin-specific protease 39 (USP39) plays a carcinogenic effect in various human tumors and can promote tumor cell growth, invasion, and migration." (PMID 35309319, 2022). "In the U251‐shUSP39‐bearing tumor, the expression levels of USP39 and ADAM9 were downregulated compared with that in the U251‐shNC‐bearing tumor." (PMID 33811456, 2022). "In conclusion, we demonstrated that USP39 is commonly upregulated in ESCC, and that it promotes malignant tumor properties in ESCC both in vitro and in vivo." (PMID 34123832, 2021). "Deregulation of the deubiquitinase USP39 and the E3 ubiquitin ligase TRIM26 plays an essential role in tumor progression." (PMID 33649471, 2021). "The results showed that USP39 knockdown led to an obvious reduction in tumor metastasis, while TRIM26 downregulation enhanced the tumor metastasis and reversed the reduction of shUSP39-related cell metastasis and the number of nodules in the lung." (PMID 33649471, 2021). "Regarding the growth of OS primary tumor, USP1, USP22 and USP39 have been shown to participate in the control of OS cell proliferation." (PMID 34571917, 2021). "We also assessed the correlation between USP39 expression and 364 HCC patients’ clinicopathological parameters such as tumor grade and prognosis based on the TCGA database." (PMID 33649471, 2021). "In detail, USP39 inhibits ZEB1 degradation through its deubiquitination function to promote HCC progression and TRIM26 degrades ZEB1 via ubiquitination to exert tumor-suppressive functions." (PMID 33649471, 2021). "On the other hand, USP39 influences the function of transcriptional co-activator with PDZ-binding motif (TAZ), which is one of the Hippo tumor suppressor pathway’s proteins." (PMID 32882786, 2020). "To examine the effect of USP39 on cell growth in vivo, we generated an orthotopic tumor model by implanting U87MG- and P3-NC/-sh-USP39-1 cells in the brains of nude mice." (PMID 31332287, 2019). "We examined the TCGA data and found that expression of USP39 was elevated in tumor tissues compared to the non-neoplastic counterparts, and that higher expression of USP39 correlated with poor survival." (PMID 39695108, 2024). "While its role has been extensively studied in tumor types like endometrial, cervical, and hepatocellular carcinoma, its function in NSCLC remains poorly understood, and no direct deubiquitination of metabolic targets have been reported for USP39 in NSCLC yet." (PMID 39695108, 2024). "We have shown that the DUB USP39 acts as a regulator of the PDHA subunit of the PDH complex, governs pyruvate conversion to the TCA cycle, and USP39 depletion has a tremendous effect on the TCA cycle, mitochondrial respiration, cell and tumor growth." (PMID 39695108, 2024). "In contrast, other demographic factors, including age, gender and tumor location were independent of USP39 expression." (PMID 34123832, 2021). "Furthermore, we assessed the OS prognostic values of USP39 in different subtypes of HCC, including T stage, N stage, M stage, pathological stage, histologic grade, residual tumor, tumor status, and vascular invasion, using Kaplan–Meier analysis." (PMID 34987596, 2021). "As previously reported, the expression of USP39 was increased in HCC tumor tissues compared with that in adjacent nontumor tissues." (PMID 34987596, 2021). "However, in tumor cells treated with DDP, overexpression of USP39 was able to reduce the apoptosis rate, suggesting that USP39 may influence the effect of cisplatin through a certain regulatory mechanism, which requires further research to clarify." (PMID 40672756, 2025).
tumor (continued). "Moreover, in tumor-infiltrating regulatory T cells (Tregs), USP39 has been identified to increase RNA splicing-mediated CTLA-4 expression, which in turn enhances the immunosuppressive function of Tregs, thereby suppressing anti-tumor immunity." (PMID 40990019, 2025). "MRPL35 expression was stabilized by USP39‐induced deubiquitination in NSCLC cells, and knockdown of MRPL35 suppressed NSCLC cell proliferation, invasion, and glutamine metabolism in vitro and impeded tumor growth in vivo by upregulating SLC7A5, providing a promising therapeutic target for NSCLC." (PMID 38987867, 2024). "Mechanically, it is up-regulated in tumor tissues and binds to NAT10, recruiting ubiquitin specific peptidase 39 (USP39) to block NAT10 ubiquitination-dependent degradation,thus promoting the formation of ac4C modification in mRNA, enhancing gene expression and leading to tumor occurrence." (PMID 38233930, 2024). "In addition, In vivo tumor formation assays showed that elevated levels of DNAAF5 promote HCC cell proliferation rates, and after USP39 knockdown in Hep3B-ov-DNAAF5 cells, the increased tumor volume due to increased expressions of DNAAF5 was significantly decreased." (PMID 36276075, 2022). "Besides, USP39 inhibits TAZ mRNA expression and promotes tumor growth in glioma." (PMID 32882786, 2020).
infection (5 papers, 2015 to 2022). The state of being infected such as from the introduction of a foreign agent such as serum, vaccine, antigenic substance or organism. "Analysis of gene expression microarray data indicated that, when the level of USP39 mRNA was decreased more than four‐fold by infection with shRNA, there were 1242 genes whose expression decreased or increased more than two‐fold." (PMID 33811456, 2022). "After infection of USP39 shRNA, MTT assay was performed in TT cells for five consecutive days." (PMID 26303214, 2015).
hematological malignancies (1 paper, 2024). "Although the function of the ubiquitinated TRIM26 protein has not yet been studied in the context of hematological malignancies, the importance of the USP39/ZEB1/TRIM26 axis deserves to be investigated in the context of MM." (PMID 39736693, 2024).
USP39 also shares sentences with these, for which no sentence is quoted: clear cell renal cell carcinoma (2 papers); renal carcinoma (2); adenovirus infection (1); atrial fibrillation (1); brain diseases (1); cardiovascular diseases (1); Cognitive impairment (1); coronary artery disease (1); depression (1); Intellectual disability (1); memory impairment (1); non-alcoholic steatohepatitis (1); oligodendroglial tumor (1); oligodendroglioma (1); pancreatic ductal adenocarcinoma (1); retinitis pigmentosa (1).